RUNX2 (RUNX family transcription factor 2)
Diseases named in the same sentence as RUNX2 in open-access papers (continued):
Sharing a sentence is not in itself a finding about the gene and the disease.
cancer (continued). "RUNX2 is linked to many human cancers including breast, prostate, and bone cancer and also cancer metastasis in bone." (PMID 26380245, 2015). "Together, it is likely that RUNX2 is tightly linked to drug-resistant phenotype of malignant cancers." (PMID 26512706, 2015). "This is further supported by the association of changes in RUNX2 expression with numerous cancers and correlation between over-expression of RUNX2 and poor prognosis in some malignances." (PMID 25244015, 2014). "The Runt-related transcription factor Runx2 is essential for bone development but is also implicated in progression of several cancers of breast, prostate and bone, where it activates cancer-related genes and promotes invasive properties." (PMID 22537242, 2012). "Transcriptome profiling using whole genome expression array followed by in silico analysis indicated that Runx2 upregulated a multitude of genes with prominent cancer associated functions." (PMID 20863401, 2010). "As Runx2 was localised in the cancer cells and the associated fibroblasts in PDAC tissues, next the effects of coculture with or without direct cell-to-cell contact between Panc-1 cells and IPSCs were analysed." (PMID 17876328, 2007). "Cancers of the breast tissues are associated with highly elevated RUNX2 and its target genes." (PMID 41459628, 2026). "Several studies have implicated RUNX2 in the progression of various malignant tumors." (PMID 40386045, 2025). "RUNX2 is thought to be associated with human osteosarcoma progression, breast cancer-mediated bone metastasis and has also been reported to related with poor prognosis in cervical, bladder and pancreatic cancer." (PMID 39822248, 2024). "Overall, RUNX2 is commonly associated with poor survival and could serve as an independent prognostic marker in multiple types of cancer." (PMID 38430423, 2024). "Notably, the nuclear labeling index (LI) of Runx2 in carcinoma cells exhibited associations with the clinical stage, histological grade, and HER2 status of the patients under examination." (PMID 37759471, 2023). "Blockade of SNAT2 could selectively affect the synthesis of proline-rich proteins such as the transcription factor RUNX2, which have been implicated in cancer cell proliferation and migration." (PMID 36210829, 2022). "RUNX2 is a member of the mammalian Runt related transcription factor family, which have important roles in cancer development 25, however, precise RUNX2 functions and associated mechanisms in NPC remain unclear." (PMID 34093832, 2021). "Recently, extensive research has shown that Runx-2 is associated with metastasis of diverse types of cancers, such as breast and melanoma cancers, which are also potential targets for novel antimetastatic agents and diagnostic approaches for detecting cancer." (PMID 30105080, 2018). "Runx transcription factors (Runx1, Runx2 and Runx3) are critical regulators of organogenesis and cell differentiation regulatory pathways, and mutations in these genes are associated with several cancers." (PMID 22537242, 2012). "RUNX2 performs proliferation-related functions in osteoblasts that may be linked to its biological activities in human cancers." (PMID 21029421, 2010). "In addition, the study discovered that ANCR is negatively linked with RUNX2 expression in cancer of the breast tissues and many cell lines, suggesting that it may have a role in the TGF‐β signal pathway." (PMID 41459628, 2026). "Similarly, RUNX2, another TF hub that has a dual transcriptional role (i.e., can act as an activator or a repressor), bound both to the promoters of genes associated with poor and good cancer prognosis." (PMID 39013578, 2024).
cancer (continued). "Recently discovered RUNX2 somatic mutations, expressional signatures of RUNX2 in normal tissues and tumors, and the prognostic and clinical significance of RUNX2 in many types of cancer have attracted attention and led RUNX2 to be considered a biomarker for cancer." (PMID 37108164, 2023). "However, it remains unknown if RUNX2 overexpression is causally relatedly to genomic instability and mutational accumulation in human cancers." (PMID 37190015, 2023). "While the role of Runx1 during kidney development is unknown, it is activated in kidney during injury and repair where it may contribute to several disease processes, including cancer, in which it may collaborate with Runx2 to drive EMT associated with worse outcomes." (PMID 34111109, 2021). "Furthermore, because RUNX2 is essential for osteogenesis, it has been suggested that association with cancers that preferentially metastasise to bone might be due to osteomimicry." (PMID 24626992, 2014). "We showed that RUNX2 controls both cancer cell catabolism and anabolism by repressing oxidative phosphorylation (OXPHOS) while promoting lipid biosynthetic pathways." (PMID 41174748, 2025). "In line with the transcriptomic data, this analysis showed a massive reorganization of the cancer cell lipid profile following RUNX2 silencing." (PMID 41174748, 2025). "Embryonic transcription factors that are re-activated in cancer, and RUNX2, despite being a typical regulator of osteogenesis, promotes metastasis through trans-differentiation processes like epithelial-to-mesenchymal transition (EMT) and osteomimicry." (PMID 41511334, 2025). "Despite its essential role, a comprehensive description of the transcriptional landscape governed by RUNX2 in cancer and a model that describes how its transcriptional function translates into meaningful biological effects have yet to be established." (PMID 41174748, 2025). "At the clinical level, RUNX2 is a central transcription factor involved in bone diseases and cancers." (PMID 41511334, 2025). "By combining omics data with functional validation, we demonstrated that RUNX2 drives cancer cell metabolic rewiring by repressing mitochondrial respiration while promoting anabolic processes." (PMID 41174748, 2025). "In skeletal disorders, RUNX2 is strongly influenced by mechanical loading, whereas in cancer, vascular mineralization, and inflammatory cartilage degeneration, RUNX2 dysregulation is more dependent on metabolic, inflammatory, or developmental cues." (PMID 41511334, 2025). "In this work, by employing cutting-edge genomic approaches followed by functional validations, we elucidated the genomic functions of RUNX2, shedding light on the mechanisms through which this TF promotes cancer progression." (PMID 41174748, 2025). "Multiple signaling pathways, including the PI3K/AKT pathway, have been reported to mediate the role of RUNX2 in cancer invasion." (PMID 40332124, 2025). "Like other embryonic TFs, RUNX2 is aberrantly reactivated in cancer, where it supports survival and metastasis." (PMID 41174748, 2025). "Pharmacological inhibition of AKT1 not only diminishes RUNX2 expression but also impairs the maintenance of cancer stem-like cell populations, indicating therapeutic sensitivity of this regulatory mechanism." (PMID 40862758, 2025). "One promising therapeutic target is the protein RUNX2, which has been shown to promote the progression of cancers, including OSCC." (PMID 40498062, 2025). "Collectively, RUNX2 is activated across different tissues such as bone, cartilage, vasculature, and cancer." (PMID 41511334, 2025). "The five EMRGs in our model—LOXL2, RUNX2, NCKAP1L, WFS1, and SPTBN1—have been implicated in diverse cancer-related processes." (PMID 41164190, 2025).
cancer (continued). "In conclusion, our data provide strong evidence supporting the role of RUNX2 in the transcriptional control of cancer cell metabolism, and in particular in promoting lipid biosynthesis." (PMID 41174748, 2025). "Through cell type annotation and manual demarcation of the carcinoma region, we quantified the proportion of RUNX2+ exhausted CD8+ T cells." (PMID 41382107, 2025). "RUNX2-suppressor of mothers against decapentaplegic (Smad) and Runx2-c-Jun interact to increase IL-11 gene expression, which promotes cancer-induced osteolytic bone disease." (PMID 38745115, 2024). "We also showed that LC regulates Runx2 ubiquitination through DTX3L, leading to a decrease in COL1A1 and alleviating SMF caused by cancer cachexia." (PMID 39091264, 2024). "All these features have already been reported as a central part of the pro-tumorigenic function of RUNX2 in cancer." (PMID 39271656, 2024). "LC inhibited the increase in Runx2 protein induced by cancer in both the in vivo mouse model and fibroblasts treated with TGF‐β1." (PMID 39091264, 2024). "In general, all of these different sources note the overexpression and oncogenicity of the Runx2 factor in various types of cancers." (PMID 39595568, 2024). "Recently, there has been increasing evidence that Runx2 has oncogenic properties in various types of cancer." (PMID 39595568, 2024). "circRUNX2.2 was generated from exon 6 of the RUNX2 gene, a member of the Runt domain family of transcription factors, and played crucial roles in osteoblast development and cancers." (PMID 39519039, 2024). "In this study, we found that LC alleviates fibrosis through the DTX3L/Runx2/COL1A1 axis in our models of cancer cachexia." (PMID 39091264, 2024). "Elevated levels of RUNX2 consistently serve as an adverse prognostic marker across multiple cancer types." (PMID 38430423, 2024). "MiR-30a is also known to negatively target RUNX2 in CS cells, inhibiting this gene to enhance cancer invasion." (PMID 38542153, 2024). "Aberrantly reactivated during oncogenesis, RUNX2 contributes to cancer aggressiveness in many settings by regulating multiple aspects of cancer cell biology." (PMID 39271656, 2024). "As RUNX2, many of these TFs have already been reported to support cancer aggressiveness in other cancers." (PMID 39271656, 2024). "circRUNX2.2 was generated from exon 6 of the RUNX2 gene, a member of the Runt domain family of transcription factors that was involved in the development of skeleton and malignant tumors." (PMID 39519039, 2024). "Noticeably, these biological processes included many genes already known to be key RUNX2 targets in TC and other cancer settings." (PMID 39271656, 2024). "This study revealed a previously unrecognized link between Runx2 and DTX3L in SMF and demonstrated that l‐carnitine exerted a significant therapeutic impact on cancer cachexia‐associated SMF, potentially through the upregulation of DTX3L." (PMID 39091264, 2024). "In this context, RUNX2 supports cancer cells’ proliferation, migration, invasiveness, and metastatic spreading." (PMID 39271656, 2024). "RUNX2 is a well-known master regulator of osteoblast and chondrocyte differentiation, but new findings have demonstrated its participation in cancer progression and tumorigenesis." (PMID 37108164, 2023). "While most studies on RUNX2 and bone destruction focus on the influence on osteoclasts, the interaction between cancer cell-derived RUNX2 and osteoblasts is not well understood." (PMID 36897488, 2023). "It has been established that RUNX2 mRNA expression is greater in cancer samples than in normal human osteoblasts." (PMID 37370857, 2023). "Overexpression of RUNX2 in a rescue assay facilitated cancer cell proliferation, as judged by increased EdU-positive rates." (PMID 37108164, 2023). "The expression of RUNX2 in 14 of 32 cancers was also found to have modified relative to that in the corresponding normal tissues, which included increased expression in 11 cancers and decreased expression in 3 cancers." (PMID 36321611, 2023).
cancer (continued). "LncRNA HCG18 silencing led to a decrease in cancer cell proliferation, which effect was abolished by RUNX2 overexpression." (PMID 37108164, 2023). "We expect this review to shed light on the recent mechanistical findings and modulatory role of RUNX2 in cancer progression and provide biological information that can guide new research in this field." (PMID 37108164, 2023). "This suggests that RUNX2 expression fosters a glycolytic phenotype, typical of many cancer cells, which is known as the Warburg effect." (PMID 38203666, 2023). "The cancer associated biological function of some were known little about, such as CBX2, CBX5, CDT1, TOPBP1 and RUNX2, but whose implication in cancer worth further exploration based on emerging evidences." (PMID 37917664, 2023). "RUNX2 modifies multiple pathways and can indirectly be involved in angiogenesis, cancer metastasis, proliferation, and drug resistance." (PMID 37759706, 2023). "With the deepening of research, evidence has indicated the correlation between RUNX2 and bone destruction in cancers." (PMID 36897488, 2023). "Accumulated experimental data have revealed the functions of the RUNX2-mediated downstream axis in modulating angiogenesis, cancer metastasis, proliferation, cancer stemness, and drug resistance leading to cancer progression." (PMID 37108164, 2023). "Different from its function of promoting bone formation in osteoblasts, cancer cell-derived RUNX2 was found to have an adverse effect on cancer-related bone destruction." (PMID 36897488, 2023). "Because core TFs for a particular cancer type tend to form an interconnected circuitry or network, it is crucial to identify other TFs within the core circuitry of OS that interact with RUNX2 and RUNX3 to promote cell survival." (PMID 37491298, 2023). "CADD522, a molecular inhibitor of the runt-related transcription factor 2 (RUNX2) transcription factor, was found to target the enzymatic F1 subunit of the ATP synthase complex to kill cancer cells by regulating ROS levels and thereby inducing apoptosis." (PMID 37954849, 2023). "Specifically, it has been reported that RUNX2 in cancer cells can recruit HDAC6 to suppress transcription." (PMID 37754231, 2023). "RUNX2 is a Runt-related transcription factor, and it was aberrantly activated in cancer progression." (PMID 37766868, 2023). "Evidence indicates RUNX2 as a poor prognostic factor in cancers, and our findings in MM support this." (PMID 36897488, 2023). "WIPI2, COL4A2, HDAC4, CUGBP2, PTPRN2 and RUNX2 are Top 6 differential methylation genes, and all of them were reported to take part in regulation of cancers." (PMID 36817452, 2023). "RUNX2 has promigratory effects on breast, prostate, and thyroid cancer cells, osteosarcoma, and melanoma cells and has emerged as a key regulator of cancer metastasis." (PMID 37190015, 2023). "RUNX2-guided signaling axes were found to participate in the modulation of several key processes of cancer progression including transdifferentiation and cancer stemness, angiogenesis, cancer cell metastasis, proliferation, and drug resistance." (PMID 37108164, 2023). "In ccRCC, RUNX2 triggered cancer cell proliferation via SCD1-dependent Wnt/β-catenin pathway activation." (PMID 37108164, 2023). "The connective tissue growth factor (CTGF) reduces the ubiquitination-dependent degradation of RUNX2 and promotes RUNX2 acetylation in cancer cells, stabilizing RUNX2 and thereby increasing the production of RANKL and MMPs." (PMID 38435029, 2023). "Knockdown of RUNX2 by siRNA revealed a decrease in cancer cell proliferation accompanied by an increase in store-operated calcium entry (SOCE)." (PMID 37108164, 2023). "On the other hand, RUNX2 was found to be harmful in seven cancer types: BLCA, KIRC, KICH, LGG, MESO, SARC, and UVM (all p<0.05)." (PMID 35522574, 2022). "In contrary to RUNX1 and RUNX3, RUNX2 promoted cancer cell recruitment and adhesion in bone and further facilitated bone colonization." (PMID 36092942, 2022).
cancer (continued). "MRNA expression of SPP1, VEGFA, POSTN, CD44, FOXO1, and RUNX2 genes was significantly change with the cancer stages of the patients." (PMID 36424413, 2022). "Our results of Runx2-mediated tubulin acetylation revealed a novel mechanism by which Runx2 can promote the bone metastatic phenotype in addition to regulating cancer-related genes." (PMID 35884497, 2022). "Since increased proliferation and invasion are essential hallmarks of cancer, our results thus suggest that by overexpressing TRβ1, or silencing Runx2 in ML-1 cells, their aggressive characteristics change towards a more less aggressive, normal phenotype." (PMID 36497320, 2022). "Our study provides evidence of a novel role of Runx2 in the regulation of microtubule stability in cancer cells." (PMID 35884497, 2022). "For instance, P38-MAPK pathway and Runx2 regulate genes involved in cell migration pathway affecting cancer progression and migration." (PMID 35820925, 2022). "We found that RUNX2, MTA1, or CUL4B depletion inhibited the proliferation of cancer cells, whereas RUNX2, MTA1, or CUL4B overexpression significantly promoted proliferation." (PMID 35534547, 2022). "Our research provides a new transcription regulatory model and a novel molecular basis for RUNX2 in carcinogenesis and metastasis, suggesting that RUNX2 is a potential therapeutic target for cancer treatment." (PMID 35534547, 2022). "In distinction to these well-established transcriptional controls of gene expression, we have uncovered a unique activation model of transcription factors between tyrosine kinase ABL and RUNX2, an osteoblastic master transcription factor, for cancer invasion." (PMID 34136397, 2021). "In BC cells, miR-30 inhibition enhances tumorigenesis and metastasis by targeting UBC9 and ITGB3 and osteomimicry of cancer cells by targeting RUNX2, ITGA5 and CDH11." (PMID 33800656, 2021). "RUNX2 played an important role in the regulation of cancer cell invasion and migration, and recent studies revealed the involvement of RUNX2 in microenvironment remodeling." (PMID 34151937, 2021). "In distinction to these well-established transcriptional controls of gene expression, we have uncovered a unique activation model of transcription factors between tyrosine kinase ABL and RUNX2 required for cancer invasion." (PMID 34136397, 2021). "The binding of SNHG3 and miR-539 can upregulate the expression of its target gene, runt-related transcription factor 2 (RUNX2), to promote cancer cell proliferation." (PMID 34778084, 2021). "In vitro cell experiments found that the enhanced activity of the RUNX2 promoter can enhance the activity of alkaline phosphatase, thereby promoting calcification and the migration and invasion of cancer cells." (PMID 34595349, 2021). "RUNX2 has been identified to promote cancer cell metastasis by increasing expression of the matrix metalloproteinases and further causing collagen degradation." (PMID 33787057, 2021). "In the present study, we uncovered a new regulatory mechanism of cancer invasion by linking ABL to RUNX2 and MMP13." (PMID 34136397, 2021). "In this study, we proved that Runx2 as an oncogene enhanced proliferation and migration of ccRCC cells by inhibiting the transcription level of tumor suppressor NOLC1, revealing a novel oncogenic mechanism of Runx2 in cancer progression." (PMID 33767130, 2021). "The LUAD maker NKX2-1 was reported to suppress LUAD progression, whereas RUNX2 was reported as key regulator to promote cancer progression." (PMID 34001209, 2021). "RUNX2 is involved in the occurrence and development of a variety of cancers, including CRC, and plays a role as an oncogene." (PMID 34778084, 2021).